UGT2A3 (UDP glucuronosyltransferase family 2 member A3)
Description:
UDP-glucuronosyltransferase (UGT) that catalyzes phase II biotransformation reactions by conjugating glucuronic acid to lipophilic substrates, thereby increasing their water solubility and facilitating excretion. Catalyzes the glucuronidation of the bile acids hyodeoxycholic acid, deoxycholic acid, chenodeoxycholic acid, and ursodeoxycholic acid.
Synonyms: FLJ21934
Tractability: Antibody: UniProt predicts a signal peptide or a membrane-spanning region. PROTAC: its protein half-life has been measured.
Gene: Protein-coding gene on chromosome 4 (68,928,459 to 68,951,804, reverse strand). Ensembl gene ENSG00000135220.
Subcellular location: Membrane
Pathways (Reactome):
Drug ADME: Aspirin ADME
Metabolism: Glucuronidation
Gene Ontology:
Molecular function: glucuronosyltransferase activity; UDP-glycosyltransferase activity
Biological process: bile acid metabolic process; xenobiotic metabolic process
Cellular component: membrane
Genetic constraint (gnomAD): Loss-of-function variants: 53 observed, 43.86 expected, observed/expected ratio (o/e) 1.21, 90% interval 0.97 to 1.52. The upper end of that interval is the gene's LOEUF score, 1.52, which puts it in group 6 of 6, group 1 being the genes least tolerant of losing a copy. Missense variants: 726 observed, 631.3 expected, observed/expected ratio (o/e) 1.15, 90% interval 1.08 to 1.22. Synonymous variants: 242 observed, 217.15 expected, observed/expected ratio (o/e) 1.11, 90% interval 1 to 1.24.
Homologues: Orthologues: chimpanzee UGT2A3 (98% identical), macaque UGT2A3 (94% identical), guinea pig UGT2A3 (72% identical), rat Ugt2a3 (68% identical), mouse Ugt2a3 (67% identical), zebrafish ugt2a7 (50% identical), zebrafish ugt2b5 (49% identical), zebrafish ugt2b1 (49% identical), zebrafish ugt5a2 (42% identical), zebrafish ugt5b4 (40% identical), zebrafish ugt5b2 (40% identical), zebrafish ugt5a1 (40% identical), and 98 more. Paralogues in human: UGT2A2 (63% identical), UGT2B4 (63% identical), UGT2B17 (62% identical), UGT2B15 (61% identical), UGT2B7 (60% identical), UGT2B10 (59% identical), UGT2B11 (59% identical), UGT2B28 (58% identical), UGT2A1 (55% identical), UGT1A1 (44% identical), UGT1A4 (43% identical), UGT1A3 (43% identical), and 9 more.
Diseases named in the same sentence as UGT2A3 in open-access papers:
UGT2A3 is named in the same sentence as 11 diseases in open-access papers, as found by Europe PMC text mining. Sharing a sentence is not in itself a finding about the gene and the disease. The quoted sentences say what the papers report.
colorectal cancer (3 papers, 2022 to 2026). A primary or metastatic malignant neoplasm that affects the colon or rectum. "The study shows that UGT2A3 could be used as a diagnostic biomarker for colorectal cancer, exhibiting high diagnostic effectiveness." (PMID 39717480, 2024). "Some studies have demonstrated that upregulation of UGT2A3 can inhibit the proliferation and metastasis of colorectal cancer cells, potentially mediated through miR-590-3p." (PMID 39717480, 2024). "The author used colorectal cancer gene expression data from the TCGA and GEO databases to validate UGT2A3 expression differences between colorectal cancer and normal control groups." (PMID 39717480, 2024). "The author assessed the impact of UGT2A3 on the survival of colorectal cancer patients using the K-M database." (PMID 39717480, 2024). "The author analyzed the correlation between UGT2A3 expression and clinical as well as immune indicators in colorectal cancer patients." (PMID 39717480, 2024). "The AUCs for UGT2A3 as a biomarker for colorectal cancer diagnosis in the TCGA dataset and GSE83889 were 0.969 (95% CI: 0.946–0.987) and 0.999 (95% CI: 0.996–1.000), respectively." (PMID 39717480, 2024). "The study confirms that UGT2A3 is low expressed in both ulcerative colitis and colorectal cancer, suggesting that UGT2A3 may play a role in the development and progression of these disease." (PMID 39717480, 2024). "Furthermore, UGT2A3 protein was low expressed in colorectal cancer tissues in HPA data." (PMID 39717480, 2024).
colon cancer (2 papers, 2022 to 2023). "After repressing miR‐590‐3p with G4‐CSSD590, the upregulation of CLCA1, B3GNT6 and UGT2A3 inhibited the proliferation and metastasis of colon cancer cells." (PMID 36855796, 2023). "A low survival rate was observed in colon cancer patients bearing a high expression level of UGT2A3." (PMID 35333898, 2022). "Then, we analysed the expressions of CLCA1, UGT2A3 and B3GNT6 in 480 cases of colon cancer and 41 cases of adjacent tissues in the TCGA database and their effects on survival and metastasis." (PMID 36855796, 2023). "We found three candidate core, tumour, suppressor genes in colon cancer, namely, CLCA1, B3GNT6 and UGT2A3." (PMID 36855796, 2023). "To verify the role of CLCA1, B3GNT6 and UGT2A3 in colon cancer, we overexpressed these genes in HCT‐116 and Caco‐2 colon cancer cells and tested their cell phenotype, proliferation, migration and invasion ability." (PMID 36855796, 2023). "To confirm whether G4‐CSSD590 can restore the expression of CLCA1, UGT2A3 and B3GNT6 and its role in colon cancer after the adsorption of miR‐590‐3p, we transfected Ctrl CSSD, CSSD590 and G4‐CSSD590 in HCT116 and Caco‐2 cells." (PMID 36855796, 2023). "In colon cancer, we observed the simultaneous low expressions of chloride channel accessory 1 (CLCA1), UDP‐GlcNAc:betaGal beta‐1,3‐N‐acetylglucosaminyltransferase 6 (B3GNT6) and UDP glucuronosyltransferase family 2 member A3 (UGT2A3), which indicated an favourable prognosis." (PMID 36855796, 2023).
colitis (1 paper, 2024). Inflammation of the colon. "The author intends to validate these results in cell lines and to investigate in animal models whether UGT2A3 can drive the progression of colitis-associated colon cancer." (PMID 39717480, 2024). "The expression of UGT2A3 is negatively correlated with neutrophil infiltration, suggesting that UGT2A3 may influence ulcerative colitis and promote colitis-associated colorectal tumorigenesis by regulating neutrophil infiltration." (PMID 39717480, 2024).
mucinous adenocarcinoma (1 paper, 2024). An invasive adenocarcinoma composed of malignant glandular cells which contain intracytoplasmic mucin. "Results indicate that UGT2A3 is related to the primary diagnosis of colon cancer, with higher expression in adenocarcinoma and lower expression in mucinous adenocarcinoma." (PMID 39717480, 2024).
cancer (4 papers, 2021 to 2025). A tumor composed of atypical neoplastic, often pleomorphic cells that invade other tissues. "The roles of CHAD and UGT2A3 in IBD pathogenesis remain less characterized, with CHAD functions primarily established in bone metabolism and cell-cell adhesion, while UGT2A3 research has focused on cancer and drug metabolism, leaving their IBD-specific contributions largely unexplored." (PMID 40821793, 2025). "UGTs genes are upregulated in tissues associated with drug metabolism, such as cancers of the liver, kidney, intestine, and pancreas, such as UGT1A6, UGT1A9, UGT1A10, UGT2A3, UGT2B7, and UGT8, and they are significantly associated with increased overall survival in cancer." (PMID 36741721, 2022). "The high expression of UGT1A8, UGT8, UGT1A7, UGT2A3, and UGT2B15 in these cancers and its relation to good patient prognosis is very interesting and deserves further investigation." (PMID 36741721, 2022). "The roles of SLC39A5, UGT2A3 and SLC17A4 are relatively undescribed in cancer." (PMID 39556603, 2024). "Kaplan–Meier plots and logrank tests revealed that six UGT genes were significantly associated with increased overall survival (OS) rates [UGT1A1 (LUSC), UGT1A6 (ACC), UGT1A7 (ACC), UGT2A3 (KIRC), UGT2B15 (BLCA, SKCM)] or decreased OS rates [UGT2B15 (LGG), UGT8 (UVM)] in specific cancers." (PMID 34503303, 2021).
tumor (4 papers, 2023 to 2026). "The author also found that UGT2A3 is significantly positively correlated with M2 macrophages and Treg cells, and studies have shown that Macrophages M2 and Treg can promote tumor growth." (PMID 39717480, 2024). "Results showed that UGT2A3 was significantly downregulated in tumor tissues in both the TCGA COAD cohort and GSE83889, with excellent diagnostic effectiveness for colon cancer." (PMID 39717480, 2024). "A notable finding of this study is that CLCA1, UGT2A3, and ZG16—three genes highly expressed in normal colorectal tissues—are consistently downregulated in tumor tissues, suggesting that their loss may represent a coordinated event in CRC progression." (PMID 41602387, 2026). "Normal tissues showed significantly higher relative expression of CLCA1, UGT2A3, and ZG16 compared with tumor tissues." (PMID 41602387, 2026). "We identified three key genes—CLCA1, UGT2A3, and ZG16—and found that they all were downregulated in tumor tissues across the TCGA-COAD and GEO datasets, as well as in independent clinical samples." (PMID 41602387, 2026). "After the measurement of tumour size, the solid tumour tissue was fixed in formalin solution to detect the expressions of CLCA1, UGT2A3 and B3GNT6." (PMID 36855796, 2023). "Furthermore, three genes (CLCA1, UGT2A3, and ZG16) were significantly downregulated in tumor tissues." (PMID 41602387, 2026).
infection (1 paper, 2015). The state of being infected such as from the introduction of a foreign agent such as serum, vaccine, antigenic substance or organism. "In addition to immunity, genes associated with metabolism (e.g. SLC5A6, SLC2A5, UGT2A3, and PDE6C) as well as membrane proteins, like TM4SF4, were also detected with a significantly higher expression level in CE infection sheep at four hour post infection, when compared with healthy controls." (PMID 26252489, 2015).
UGT2A3 also shares sentences with these, for which no sentence is quoted: adenocarcinoma (1 paper); carcinoids (1); immune dysfunction (1); prostate carcinoma (1).